MALAT1 (metastasis associated lung adenocarcinoma transcript 1)
Diseases named in the same sentence as MALAT1 in open-access papers (continued):
Sharing a sentence is not in itself a finding about the gene and the disease.
melanoma (continued). "In conclusion, we demonstrated that MALAT1 is an oncogene in melanoma." (PMID 27564100, 2016). "In this study, the aberrant up-regulation of MALAT1 was detected in melanoma." (PMID 27564100, 2016). "Hence, in this study, we selected 6 well-documented lncRNAs associated with metastasis including MALAT1, HOTAIR, NEAT-1, HULC, MEG-3, and UCA1 to evaluate their expression in primary melanoma and matched lymph node metastasis tissues." (PMID 23862139, 2013). "We isolated several MALAT1 cDNA clones from the melanoma- and leukemia-derived tumor libraries." (PMID 23717670, 2013). "Therefore, we assessed whether the miR-34a expression affected MALAT1 expression by inhibiting miR-34a-5p in A375 melanoma cells." (PMID 40863726, 2025). "Notably, the silencing of MALAT1 is also obtained by the generation of small-molecule compounds that target this lncRNA, inducing its downregulation and suggesting the potential success of this strategy in melanoma." (PMID 40282449, 2025). "Additionally, miR-34a-5p silencing in the A375 melanoma cell line led to MALAT1 overexpression." (PMID 40863726, 2025). "However, little is known about the potential tissue-specific role of MALAT1 in melanoma." (PMID 37235843, 2023). "We aimed to investigate whether this anomaly of MALAT1 downregulation is specific to melanoma." (PMID 37235843, 2023). "Also, the role of MALAT1 in metastasis of melanoma is a hot topic that raises much attention." (PMID 33392203, 2020). "Furthermore, MALAT1 promotes melanoma cell growth and invasion by silencing miR-140 or miR-2217,23." (PMID 31101802, 2019). "Furthermore, we demonstrated a ceRNA activity of MALAT1 by modulating miR-183 in melanoma cells." (PMID 27966454, 2017). "Increased expression of MALAT1 may promote melanoma metastasis." (PMID 27564100, 2016). "MALAT1 may promotes melanoma progression in vivo by operating as a ceRNA." (PMID 27564100, 2016). "In melanoma, ASO strategy is used at the preclinical level to inhibit the expression of oncogenic MALAT1." (PMID 40282449, 2025). "Several lncRNAs, such as HOTAIR, MALAT1, and BANCR have been reported to be dysregulated in melanoma." (PMID 38561355, 2024). "Other studies identified the role of HOTAIR, MALAT1, BANCR, ANRIL, SPRY‐IT1, SAMMSON, UCA1, and SLNCR1 in melanoma patients and cell lines." (PMID 39764216, 2024). "(ρ = 0.418) MALAT1 and ERK2 expression also showed a strong correlation in both healthy skin (ρ = 0.512) and melanoma." (PMID 37235843, 2023). "The correlation between MALAT1 and NRAS expression was high in both comparisons, and even higher in melanoma." (PMID 37235843, 2023). "The correlation between MALAT1 and ERK1 was similar in strength in both melanoma (ρ = 0.401) and healthy skin." (PMID 37235843, 2023). "(ρ = 0.384) MALAT1 and MEK2 expression also showed a significant correlation in both healthy skin and melanoma (both p < 0.001)." (PMID 37235843, 2023). "To further investigate the anti-cancer effects of MALAT1 inhibition in MALAT1-downregulated cancer, we applied systemic MALAT1-ASO treatment in xenograft mouse models with NRAS-mutant melanoma tumors." (PMID 37235843, 2023). "Here, we found that MALAT1 expression was significantly correlated with ERK1 and ERK2 expression in both healthy skin and melanoma (all four comparisons: p < 0.001)." (PMID 37235843, 2023). "Previous studies have shown that MALAT1 is highly enriched in the nuclei of human cells, including NRAS mutant melanoma." (PMID 37235843, 2023). "We found that MALAT1 and MEK1 expression were significantly correlated in both healthy skin samples and melanoma (both p < 0.001)." (PMID 37235843, 2023). "To investigate additional co-regulatory mechanisms of MALAT1 expression and MAPK signaling, we measured the response of MALAT1 expression to drug-induced MAPK inhibition in two NRAS-mutant melanoma cell lines, D04 and MM415." (PMID 37235843, 2023).
melanoma (continued). "For example, several lncRNAs have been dysregulated in melanoma, including HOTAIR, BANCR, UCA1, and MALAT-1, and related to invasion and metastasis." (PMID 35626352, 2022). "Several lncRNAs were studied because of the high expression levels in melanoma patients, including SPRY4-IT1, MALAT-1, BANCR, UCA1, HOTAIR, and SNHG8." (PMID 36614156, 2022). "Many lncRNAs have been proved to be oncogenes in melanoma, such as FOXD3-AS1, NEAT1, MALAT1 and MEG3." (PMID 34247598, 2021). "By binding miR-34a and miR-22 and regulating miR-34a and miR-22 function, MALAT1 up-regulates c-Myc, Met, MMP14, and snail expression, promotes melanoma cell proliferation, invasion, and migration in vitro, and is required for melanoma progression in mice." (PMID 32174966, 2020). "In addition, MALAT1 and LINC00943 may be independent risk factors for the prognosis of patients with cutaneous melanoma and might become predictive molecules for the long-term treatment of melanoma and potential therapeutic targets." (PMID 32993558, 2020). "In addition, MALAT1 and LINC00943 may be independent risk factors for the prognosis of patients with this condition and might become predictive molecules for the long-term treatment of melanoma and potential therapeutic targets." (PMID 32993558, 2020). "Several lncRNAs are also upregulated in melanoma including SPRY4-IT1, BANCR, HOTAIR, UCA1 and MALAT-1." (PMID 29343260, 2018). "These are: MALAT1, NEAT1, PCA3, BCAR4, lncRNA-ATB (CTD−2314B22.3) and the recently-discovered melanoma driver SAMMSON (RP11−460N16.1)." (PMID 28128360, 2017). "We also found an intense positive correlation between MALAT1 and ITGB1 levels (r = 0.581, P < 0.001) in melanoma tissues." (PMID 27966454, 2017). "However, the function and molecular mechanism of MALAT1 in melanoma remains unclear." (PMID 27564100, 2016). "Our results demonstrate that NRAS expression is significantly correlated with MALAT1 expression in both non-cancerous skin (p < 0.001) and melanoma (p < 0.001)." (PMID 37235843, 2023). "To confirm the effectiveness of the MALAT1-targeting ASO in MALAT1-inhibition, we exposed NRAS-mutant D04 melanoma cells to non-targeting Control-ASO or MALAT1-ASO at a concentration of 50 nM for one day." (PMID 37235843, 2023). "The large-scale analysis presented here indicates that the correlation of MALAT1 and MAPK kinase gene expression increases in melanoma and the relative expression of MALAT1 to the MAPK-pathway genes NRAS, BRAF, MEK1, MEK2, ERK1 and ERK2 is strongly reduced in melanoma, when compared to healthy skin." (PMID 37235843, 2023). "Although the precise role of MALAT1 in MAPK-signaling remains largely unknown, our findings suggest the presence of multiplexed oncogenic functions of MALAT1 in melanoma and other types of cancer." (PMID 37235843, 2023). "MALAT1 consists of sequence-specific miR-34a- and miR-22-binding sites, binds miR-34a and miR-22, and regulates miR-34a and miR-22 function, leading to up-regulation of c-Myc, Met, MMP14, and snail in melanoma cells." (PMID 32174966, 2020). "MALAT1 is over-expressed in human melanoma compared to adjacent normal tissues, and MALAT1 expression negatively correlates with miR-34a expression in melanoma tissues." (PMID 32174966, 2020). "Other lncRNAs involved in melanoma cell proliferation are LLME23, UCA1 and MALAT1." (PMID 30499222, 2019). "Levels of UCA1 and MALAT-1 were significantly upregulated in melanomas compared to normal controls, and were significantly higher at later stage (stage III and IV) compared to early stage melanomas (stage I and II)." (PMID 29343260, 2018). "We then explored that MALAT1 may serve as “sponge ceRNA” to adjust the expression of ITGB1 and tumor growth through inhibiting the expression of miR-183 in melanoma cells, providing a new insight in the therapy of malignant melanoma." (PMID 27966454, 2017).
melanoma (continued). "Here, we identified that MALAT1 was highly expressed in melanoma tissues and cells compared with the non-cancer skin or normal cells." (PMID 27966454, 2017). "MALAT1 and UCA1 are upregulated in melanoma and both may indicate lymph node metastasis in melanoma." (PMID 28415644, 2017). "We also detected the expression of MALAT1 in human epidermal melanocytes (HEMa-LP) and three human melanoma cell lines (A375, SK-MEL-5 and SK-MEL-2), and found that MALAT1 was significantly higher in melanoma cells than in human epidermal melanocytes, especially in A375 cells." (PMID 27564100, 2016). "We predicted there are no miR-18b (a tumour suppressor in melanoma) binding site in MALAT1 transcripts." (PMID 27564100, 2016). "However, the role of MALAT1 in regulation of gene and protein expression of the MAPK-pathway kinases RAS, RAF, MEK and ERK in melanoma is largely unknown." (PMID 37235843, 2023). "First, we tested MALAT1-ASO treatment in a panel of twelve non-resistant melanoma cell lines, that have a variety of MAPK cancer-driving mutations (NRASQ61L, NRASQ61R, NRASQ61K, NRASG12D, NRASG12V, BRAFV600E and BRAFD594G), including two primary patient-derived cell lines (AV5 and Hs852T)." (PMID 37235843, 2023). "However, MALAT1-inhibition did not significantly affect NRAS RNA levels in NRAS-mutant melanoma cells." (PMID 37235843, 2023). "Using a large panel of patient-derived tissue samples, we further show that MALAT1 expression correlates significantly with RNA expression of genes coding for the MAPK-pathway key kinases NRAS, BRAF, MEK1/2 and ERK1/2 in healthy skin, and notably to a greater extent in melanoma." (PMID 37235843, 2023). "To gain further insight into the potential interactions between MALAT1 and MAPK pathway signaling regulators, we analyzed the expression patterns of MALAT1 with NRAS, BRAF, MEK1, MEK2, ERK1 and ERK2 in a large dataset of healthy skin and melanoma patient samples." (PMID 37235843, 2023). "For instance the axis MALAT1/miR-211/SIRT1 is increased in vitiligo keratinocytes, protecting these cells from UVB-induced DNA damage and promoting their differentiation which correlate with a lower incidence of melanomas and other cancers in vitiligo patients." (PMID 35883477, 2022). "After confirming MALAT1 upregulation in amoeboid cells, we went further and investigated whether downregulation of MALAT1 could induce AMT in A375m2 melanoma cells with a well-established amoeboid phenotype, and also in A2058 cells, another morphologically amoeboid melanoma cell line." (PMID 32369931, 2020). "Moreover, it has been shown that MALAT1 is intensively related to lymph node metastasis, and UCA1 is correlated with advanced melanoma, which indicates that lncRNAs may be effective biomarkers for identifying metastasis of SKCM." (PMID 33392203, 2020). "Thus, the expression of MALAT1, LINC00943 and LINC00261 is increased in melanoma and may be responsible for the tumorigenesis of melanoma." (PMID 32993558, 2020). "Collectively, these data indicated that MALAT1 may act as an endogenous ‘ceRNA’ through binding to miR-183, thus eliminating the miR183-mediated inhibitory effects on the ITGB1 expression and its downstream signalling events in melanoma." (PMID 27966454, 2017). "Furthermore, we also found a strong negative correlation between MALAT1 and miR-183 expressions (r = -0.626, P < 0.001) in malignant melanoma tissues." (PMID 27966454, 2017). "MALAT1-ASO treatment significantly inhibited colony formation in vitro and reduced tumor growth in an NRAS-mutant melanoma xenograft mouse model in vivo, while showing no aberrant toxic side effects." (PMID 37235843, 2023). "MALAT1 and BRAF expression was significantly correlated in both non-cancerous skin (p < 0.001) and in melanoma (p < 0.001), with the correlation being even stronger in melanoma." (PMID 37235843, 2023).
multiple myeloma (54 papers, 2014 to 2025). "For example, resveratrol targets metastasis associated lung adenocarcinoma transcript 1 (Malat1) in Parkinson’s disease and noncoding nuclear-enriched abundant transcript 2 (Neat1) in myeloma." (PMID 37796408, 2023). "In multiple myeloma, metastasis associated lung adenocarcinoma transcript 1 (Malat1) which has been proved to play a role in various cancers, inhibited NRF2 via activation of their negative regulator KEAP1149." (PMID 32709863, 2020). "This study aimed to investigate the role and clinical relevance of the long non-coding RNA (lncRNA), metastasis-associated lung adenocarcinoma transcript 1 (MALAT1) in multiple myeloma." (PMID 25369863, 2014). "The biological process with the highest correlation with C1 IGHG4+ Myeloma Cells was subunit; The biological process most associated with C2 MALAT1+ Myeloma Cells was biosynthetic; The biological process most associated with C3 IGHG1+ Myeloma Cells was electron." (PMID 39281682, 2024). "Moreover, additional studies are needed to correlate all the findings obtained in MM cell lines with the phenotypes observed in patients, especially regarding migration of FAM46C‐mutated myeloma cells and its relation with MALAT1 up‐regulation." (PMID 32141701, 2020). "Another possible explanation for the higher expression of MALAT1 in the current study may be associated with the bone marrow microenvironment which supports the proliferation of myeloma cells." (PMID 25369863, 2014). "In addition, the change in MALAT1 expression after treatment was clinically significant and may serve as a molecular predictor of the patients at risk of early progression of multiple myeloma." (PMID 25369863, 2014). "And the 14-nt linear-type sgRNA sgRM3 was designed at the site where an ASO has been shown to effectively reduce the MALAT1 level in human myeloma cells." (PMID 40966253, 2025). "And downregulation of the MALAT1 RNA level by conventional ASOs has been shown to suppress metastasis of human lung cancer cells or growth of human myeloma cells in a mouse xenograft model." (PMID 40966253, 2025). "The four identified cell subgroups were as follows: C0 IGLL5+ Myeloma Cells (724 cells), C1 IGHG4+ Myeloma Cells (310 cells), C2 MALAT1+ Myeloma Cells (305 cells), and C3 IGHG1+ Myeloma Cells (149 cells)." (PMID 39281682, 2024). "MALAT1 is strongly expressed in several cancers, such as stomach, colon, ovarian, chronic myeloid leukemia, and myeloma." (PMID 40034935, 2024). "An LNA gapmer displays a greater than 50-fold decrease in MALAT1 levels upon treatment in multiple myeloma cells, which is accompanied with reduced cell proliferation and increased apoptosis." (PMID 38338910, 2024). "In multiple myeloma (MM), the transcription factor Sp1 can be recruited by MALAT1 to promote the secretion of TGF-β by binding to latent transforming growth factor-β binding protein-3." (PMID 36829256, 2023). "Some of these lncRNAs affected cell metabolism (e.g., high expression of MALAT1‐accelerated glycolysis), whereas some lncRNAs influenced myeloma cell invasion." (PMID 36057947, 2023). "Specifically, MALAT1 targets miR-188-5p to affect cell proliferation and apoptosis in multiple myeloma." (PMID 36700468, 2022). "It has been reported that MALAT1 is involved in the repair pathway of DNA double-strand breaks, and targeting MALAT1 can induce apoptosis in myeloma cells." (PMID 34778078, 2021). "In multiple myeloma, MALAT1 regulates proliferation and adhesion of multiple myeloma cells via hsa-miR-181-5p/Hippo-YAP axis." (PMID 35008626, 2021). "They showed a dysregulation of plasma lincRNA-p21 levels in CLL patients and taurine upregulated gene 1 (TUG1), metastasis associated lung adenocarcinoma transcript 1 (MALAT1), HOX transcript antisense RNA (HOTAIR) and GAS5 in multiple myeloma patients." (PMID 33593440, 2021). "Treatment with siRNA against MALAT-1 increased apoptosis of the multiple myeloma tumor cells, which was attenuated by expression of HMGB1." (PMID 34680084, 2021).
multiple myeloma (continued). "In multiple myeloma cells, HMGB1 was found to associate with the lncRNA MALAT-1 in a pull-down assay." (PMID 34680084, 2021). "MALAT1 gapmer oligonucleotides conjugated to single- walled carbon nanotubes delivered systemically into mice resulted in significant inhibition of multiple myeloma growth." (PMID 32503170, 2020). "In multiple myeloma, MALAT1 was shown to be a target of KDM3A, whose upregulation resulted in accumulation of HIF-1α, and induction of glycolytic genes under hypoxia conditions." (PMID 32503170, 2020). "LncRNA MALAT1 facilitated the tumorigenesis, invasion and glycolysis of multiple myeloma via miR‐1271‐5p/SOX13 axis." (PMID 32515146, 2020). "Of the lncRNAs discussed here, MALAT1 (in prostate cancer and multiple myeloma), HOTAIR (in NSCLC and multiple myeloma), and SPRY4-IT1 (in esophageal squamous-cell carcinoma) have been implicated as relevant biomarkers in liquid biopsies." (PMID 32244924, 2020). "MiR-181a-5p has previously been found to be a target of LncRNA MALAT1, whose interference decreased the expression of miR-181a-5p and inhibited the proliferation and adhesion of myeloma cells." (PMID 32916955, 2020). "MALAT1 has also been shown to epigenetically upregulate transcriptional activators of proteosome subunit genes in multiple myeloma cells." (PMID 32503170, 2020). "Knockdown of MALAT1 inhibits LTBP3 transcription and TGF-β secretion in MSCs from the bone marrow of myeloma patients, whereas overexpression of MALAT1 increases LTBP3 transcription and TGF-β secretion in MSCs from healthy donors." (PMID 31717266, 2019). "In multiple myeloma cells, lncRNA MALAT1 transcript activates LTBP3-regulated molecules in tumor suppressor and oncogenic pathways." (PMID 27090737, 2016). "The expression level of MALAT1 is correlated with tumorigenesis and metastasis in solid cancers and multiple myeloma, suggesting a universal cancer role." (PMID 27998273, 2016). "For the post-treatment patients with a VGPR or CR (n = 33), a smaller MALAT1 change (difference in ∆CT ≤1.5) remained the single factor predictive of early progression of multiple myeloma (OR 4.38, 95% CI 1.48-12.99; p = 0.008)." (PMID 25369863, 2014). "In the current study, we demonstrated that MALAT1 was overexpressed in the patients with newly diagnosed multiple myeloma." (PMID 25369863, 2014). "The current study also investigated the clinical relevance of MALAT1 in patients with multiple myeloma." (PMID 25369863, 2014). "The strength of binding between sgRNA and target RNA would also need to be considered, since the ASO modified with locked nucleic acids that was designed to target the MALAT1 RNA at the same site as sgRM3 has been shown to effectively reduce the MALAT1 level in myeloma cells." (PMID 40966253, 2025). "Furthermore, MALAT1 has been shown to modulate the alternative NHEJ (A-NHEJ) pathway by directly interacting with LIG3 and PARP1 in multiple myeloma cells and targeting MALAT1 enhances sensitivity to PARPi or proteasomal inhibitors." (PMID 37812088, 2023). "The targeting of MALAT1 with GapmeR has recently been shown to be effective in myeloma." (PMID 35052495, 2022). "MALAT1 can recruit Sp1, a transcription factor, in multiple myeloma." (PMID 34778078, 2021). "LNA gapmeR ASO-targeting lncRNA MALAT1 possesses anti-multiple myeloma activity; (iii) CRISPR/Cas9 technology is suitable for dual-located lncRNAs, and it has been widely used in the discovery and annotation of lncRNAs but, as of yet, is not ideal for systematic drug delivery." (PMID 34168572, 2021). "More specifically, MALAT1, expressed at high levels in the MSCs from myeloma patients, was shown to recruit the transcription factor SP1 on the LTBP3 promoter contributing to the increase of LTBP3 expression, most likely by stabilizing the interaction between SP1 and SP1-consensus sequences." (PMID 27177333, 2016).